MTOR (mechanistic target of rapamycin kinase)
Diseases named in the same sentence as MTOR in open-access papers (continued):
Sharing a sentence is not in itself a finding about the gene and the disease.
epilepsy (360 papers, 2012 to 2026). A brain disorder characterized by episodes of abnormally increased neuronal discharge resulting in transient episodes of sensory or motor neurological dysfunction, or psychic dysfunction. "Given that RHEB mutations represent potentially druggable mTOR pathway targets, these findings have significant implications for individualized therapeutic strategies and precision epilepsy care." (PMID 41940182, 2026). "Pathogenic variants in the nitrogen permease regulator-like 3 (NPRL3) gene and other regulators of the mTOR pathway have been linked to diverse epilepsy phenotypes, including SHE." (PMID 41635699, 2026). "Although, in the mTOR‐hyperactivity–associated syndrome tuberous sclerosis, mTOR inhibitors have proven to be beneficial in treating epilepsy, ASD‐associated symptoms are ameliorated only partially." (PMID 40704780, 2025). "Both germline and somatic variants in genes encoding components of the mechanistic target of rapamycin (mTOR) pathway contribute to a spectrum of epilepsies (including NAFEs) and MCD." (PMID 40381056, 2025). "mTOR hyperactivation is linked to seizures, and its inhibition alleviates epilepsy in other preclinical models." (PMID 41562862, 2025). "With respect to TSC-associated ASD, a recent study reported the following: the mTOR pathway plays a crucial role in several brain processes leading to TSC-related epilepsy, intellectual disability, and autism spectrum disorder (ASD)." (PMID 39852149, 2025). "PTEN-deficient neurons exhibit hyperactivation of the mTOR pathway and pathological features resembling histopathological neurons in drug-resistant epilepsy that cause epileptic seizures." (PMID 40026248, 2025). "In utero models leading to neuronal mTOR hyperactivity influence the severity of later epilepsy and associated neuropathology of FCDs." (PMID 40996830, 2025). "Particularly, pathogenic variants of genes encoding regulators of the mammalian target of rapamycin (mTOR) cascade have been implicated in the occurrence of epilepsies, malformations of cortical development, and neurodevelopmental disorders." (PMID 40740850, 2025). "This is because hyperactivation of AKT/mTOR signaling has been extensively shown to underlie major seizure disorders, including tuberous sclerosis complex." (PMID 41562862, 2025). "In human epilepsy patients with FCD type II with identified causal mutation in the mTOR pathway, the frequency of the alternative allele has been repeatedly reported as typically between 1 and 15%." (PMID 41366489, 2025). "Further, there are well-defined monogenetic variants in genes that code for mTOR pathway proteins that lead to disrupted mTOR signaling and that have been associated with intellectual disability, epilepsy, and autism spectrum disorder." (PMID 40792287, 2025). "Mutations of the DEP Domain Containing 5 gene (DEPDC5), a mechanistic Target of Rapamycin (mTOR) inhibitor involved in amino acid sensing, are associated with neurological diseases such as epilepsy and/or autism spectrum disorder (ASD)." (PMID 40704780, 2025). "Variants affecting the mTOR pathway have been found with VAFs of as low as 1% in brain tissue resected from individuals with epilepsy and are thought to be a cause of disease." (PMID 38540392, 2024). "There is growing evidence that MAPKs and MTOR are implicated in epilepsy by phosphorylating and regulating RNA-binding proteins, for which our unbiased screen gives further support." (PMID 38600976, 2024). "Under the six-tier approach for precision therapies proposed by Byrne and colleagues, mTOR inhibitors for the treatment of TSC-associated epilepsy and solid tumors fall within Tier 3, wherein the therapy directly targets gene dysfunction." (PMID 38540392, 2024). "Upregulation of the mTOR pathway has been shown to cause malformations of cortical development, medically refractory epilepsies, and neurodevelopmental disorders, collectively described as mTORopathies." (PMID 38540392, 2024).
epilepsy (continued). "The mTOR pathway has long been a target of antiepileptic research due to genetic forms of epilepsy with mutations within the mTOR pathway (mammalian target of rapamycin; e.g., tuberous sclerosis 1/2 (TSC1/2) and phosphatase and tensin homolog (PTEN);)." (PMID 38927072, 2024). "Focal cortical dysplasia type II is typically caused by somatic mutations resulting in mammalian target of rapamycin (mTOR) hyperactivity, and is the commonest pathology found in children undergoing epilepsy surgery." (PMID 38100333, 2024). "In parallel, neurological disorders associated with dysfunction of the mTOR pathway have been reported in epilepsy, autism, and neurodegenerative diseases." (PMID 38812794, 2024). "The goal of this review will be to extrapolate and expand on the current findings of voltage-gated channels implicated in other epilepsies, where aberrant mTOR signaling occurs, while surmising their role in TSC-related seizures." (PMID 39253727, 2024). "Incidentally, hyperactive mTOR signaling is associated with epilepsy, and inhibitors of mTOR result in seizure reductions in several animal models of epilepsy and patients with epilepsy." (PMID 38398876, 2024). "Somatic mutations in the PIK3/AKT/mTOR pathway in pyramidal neurons are responsible for various brain malformations and epilepsy depending on the mutation occurrence during brain development." (PMID 36982451, 2023). "It is known that abnormal activation of the mTOR pathway can cause a number of neurological diseases such as tuberous sclerosis and epilepsy." (PMID 37273718, 2023). "Its link to Ca++ channels is also relevant here, since Ca++ channelopathies themselves often cause epilepsy, and mutations in such channel genes also impact the mTOR system." (PMID 36982355, 2023). "These mice exhibit hyperactive mTOR signaling as a result of this mutation and develop epilepsy, macrocephaly, autistic‐like behaviors and cognitive impairments." (PMID 37376966, 2023). "Due to the widely diverse number of different genetic syndromes and mutations that lead to refractory epilepsy, success rates are difficult to estimate, with better outcomes reported in mutations in the mTOR pathway." (PMID 36970544, 2023). "Exaggerated mTOR activity is associated with the development of temporal lobe epilepsy, genetic and acquired epilepsy, experimental epilepsy and Lafora disease." (PMID 37880579, 2023). "Malformations in the mTOR signaling pathway are linked to different developmental malformations such as epilepsy and autism." (PMID 36819340, 2023). "A spontaneous anatomical abnormality of the neocortex, focal cortical dysplasia type II (FCDII) is characterized by treatment-resistant epilepsy due to atypical neurons and dyslamination caused by deficient mTOR signaling." (PMID 36675042, 2023). "Our findings are similar to previous case series suggesting that epilepsy surgery can be a treatment option in patients with mTOR pathway mutation." (PMID 37574648, 2023). "Disturbances in the UPS within the context of epilepsy are associated with mTOR hyperactivation, akin to the phenomenon observed with autophagy disruption." (PMID 40217521, 2023). "Evidence-based data also recommends mTOR inhibition for managing tuberous sclerosis complex-associated epilepsy." (PMID 37240765, 2023). "Because multiple mTORopathies are commonly associated with epilepsy, mTOR signaling emerges as an important factor in its pathogenesis in several different ways." (PMID 36675042, 2023). "Several neurodevelopmental disorders are associated with increased mTOR activity that results in pathogenic neuronal dysmorphogenesis (i.e., soma and dendrite overgrowth), leading to circuit alterations associated with epilepsy and neurologic disabilities." (PMID 37620147, 2023). "NPRL3 is an important component of the GATOR1 complex, and its mutations can promote the activity of the mTOR signaling pathway, thereby causing epilepsy." (PMID 36937533, 2023).
epilepsy (continued). "In recent years, inhibition of the mTOR pathway has become a new therapeutic strategy in epilepsy because the mTOR pathway is associated with malformations of cortical development (MCD) coupled with intractable epilepsy." (PMID 36835631, 2023). "Focal cortical dysplasia is the most common malformation during cortical development, sometimes excised by epilepsy surgery and often caused by somatic variants of the mTOR pathway genes." (PMID 36864519, 2023). "Aberrant mTOR signaling strongly contributes to the pathogenesis of mTORopathies and is directly linked to epilepsy associated with these disorders." (PMID 36675042, 2023). "Genetic mutations leading to activation of the mTOR pathway is found to be the underlying etiology in TSC co-occurring with epilepsy and autism." (PMID 36819340, 2023). "One such group of neurodevelopmental disorders are mTORopathies that arise from gene variants leading to increased mTOR activity and epilepsy." (PMID 37620147, 2023). "Mutations in mTOR pathway genes (MPG) such as TSC2 and PTEN, both negative regulators of mTOR, are linked to developmental brain malformations, intellectual disability, autism, and epilepsy." (PMID 37479502, 2023). "Loss-of-function mutations in up-stream negative regulators of mTOR, activating mutations in positive regulators of mTOR, and gain-of-function mutations in mTOR itself are associated with epilepsy and cortical dysplasia." (PMID 37963879, 2023). "Exaggerated mTOR activity is associated with the development of temporal lobe epilepsy, genetic and acquired epilepsy, and experimental epilepsy." (PMID 37880579, 2023). "Some treatments such as everolimus have already been approved by the FDA for the inhibition of the mTOR pathway and are associated with a significant reduction in the frequency of epilepsy in patients with TSC." (PMID 36982349, 2023). "Like mitochondrial genes, mutations within the mTOR pathway genes are the commonest cause of epilepsy, often accompanying focal cortical dysplasia (PCD) and other cortical malformations." (PMID 36982355, 2023). "It has been shown that microglial mTOR plays a protective role in mitigating neuronal loss and attenuating epileptogenesis in the excitatory injury model of epilepsy." (PMID 37737447, 2023). "Mutations in the proteins comprising the mTOR pathway’s two multiprotein complexes mTORC1 and mTORC2 cause epilepsy and are termed mTORopathies." (PMID 36635730, 2023). "It is interesting to note the case of an epilepsy patient with a mutation in the mTOR kinase domain." (PMID 38067243, 2023). "Treatment with mTOR pathway inhibitors is an important therapeutic option in drug-resistant epilepsy associated with TSC." (PMID 35572924, 2022). "Individuals with mutations affecting synaptic transmission or ion channels (5 articles, 14 patients) were less likely to benefit from epilepsy surgery than those with mutations in the mechanistic target of rapamycin (mTOR) pathway (10 articles, 30 patients)." (PMID 35246493, 2022). "Animal model studies suggested that biallelic inactivation was necessary to cause mTOR hyperactivation, shape neuronal morphology, and generate epilepsy with focal cortical dysplasia." (PMID 35706428, 2022). "In patients with tuberous sclerosis complex (TSC) and in some focal cortical dysplasia (FCD) cases, treatment resistant epilepsy (TRE) is associated with increased activation of mammalian target of rapamycin (mTOR) signaling." (PMID 35587487, 2022). "Among various forms of epilepsy, mutations in ion channels and mTOR signaling molecules lead to converging epileptic types, ranging from focal to generalized epilepsy." (PMID 35359577, 2022).
epilepsy (continued). "Loss of the ubtor gene in zebrafish causes motor hyperactivity and epilepsy-like behaviors by elevating neuronal activity and activating mTOR signaling." (PMID 36317962, 2022). "Components along the mTOR pathway have also been shown to be a hotspot for epilepsy, reflected by its mutation displaying not only a higher firing rate, but also changes in morphology." (PMID 35359577, 2022). "Mutations along the mTOR pathway converge to changes in intrinsic neuronal excitability and synaptic inputs, aggravating the hypersynchrony in the network and leading to epilepsy." (PMID 35359577, 2022). "Summary of human iPSC-derived cultures on epilepsy related to ion channels and mTOR pathway mutations." (PMID 35359577, 2022). "Another cluster of genes often found mutated in epilepsy patients are those encoding components of the mTOR pathway, an essential regulator of cell metabolism and physiology." (PMID 35359577, 2022). "The mTOR signaling pathway is considered one of the disease mechanisms that underlie monogenic epilepsies (i.e., mTORopathy)." (PMID 35742889, 2022). "Tuberous sclerosis complex (TSC) is a congenital disorder characterized by cortical malformations and concomitant epilepsy caused by loss‐of‐function mutations in the mTOR suppressors TSC1 or TSC2." (PMID 33786950, 2021). "Hyperactivation of the mTOR pathway in the brain can cause seizures, increased anxiety and memory impairment in animal models, and in patients can cause epilepsy, autism and intellectual disability." (PMID 34381067, 2021). "In vitro functional assessments of mTOR pathway genetic variants previously detected in people with epilepsy demonstrated molecular evidence of mTORC1 hyperactivation." (PMID 34632383, 2021). "To date, pathogenic variants in 16 distinct genes encoding mTOR pathway proteins have been detected in individuals with epilepsy and/or neurodevelopmental disorders." (PMID 34632383, 2021). "Of note, the mTOR pathway which was found to be altered in GL mice has been linked to epilepsy phenotypes in humans." (PMID 34801069, 2021). "Hyperactivity of the mTORC1 pathway has been demonstrated in: experimental animal models of mTORopathies; in vitro functional assessments of epilepsy-causative mTOR pathway genetic variants; and resected brain tissue from patients with FCD and HME." (PMID 34632383, 2021). "Non-syndromic MEG with ID, with possible autism and epilepsy has been reported in about 20 individuals harboring germline MTOR mutation." (PMID 35096710, 2021). "Both genetic and acquired epilepsies have been linked to the excessive activation of the mammalian target of rapamycin (mTOR) signaling pathway." (PMID 34635103, 2021). "Overactivation of mTOR signaling is posited as a mediator of pathologies associated with epilepsy such as ectopic localization of newborn neurons into the HL, aberrant mossy fiber sprouting, and seizures." (PMID 34095131, 2021). "There is a strong suggestion in the preclinical literature of an association between mTOR activity and epilepsy/epileptogenesis, particularly in malformations of cortical development." (PMID 33643212, 2021). "The mTOR pathway has important roles in nervous system development and hyperactivation of the mTOR pathway causes neurological diseases associated with aberrant intellectual development, epilepsy and autism." (PMID 34381067, 2021). "In patients with tuberous sclerosis complex suffering from severe and treatment-resistant epilepsy, the mTOR pathway is hyperactivated due to mutations in TSC1 and TSC2 genes." (PMID 33859552, 2021). "In summary, here, we made use of a hyperactive RHEB mutant that was previously identified in patients with ID, megalencephaly, and epilepsy, as a model for human mTOR-related MCD-associated epilepsy." (PMID 34038402, 2021). "The almost complete absence of these networks in pilocarpine mice is consistent with the known role of mutations of MTOR pathway components in epilepsy." (PMID 34122302, 2021).
epilepsy (continued). "Both germline and somatic mutations in genes encoding for different components of mTOR signalling cause epilepsies, MCD and neurodevelopmental disorders." (PMID 34632383, 2021). "The delay in seizure onset indicates that other factors additional to the principal mutation and resulting cell autonomous mTOR hyperactivation cause epilepsy, such as alterations in the transcriptional profile over time." (PMID 33786950, 2021). "In the treatment of TSC-associated epilepsy in infancy, the potential efficacy of an mTOR inhibitor is theoretically expected, but still remains to be proven." (PMID 34206526, 2021). "Here, we made use of the recently identified dominant-active mutation in Ras Homolog Enriched in Brain 1 (RHEB), RHEBp.P37L, to gain insight in the mechanism underlying the epilepsy caused by hyperactivation of the mTOR pathway." (PMID 34038402, 2021). "In summary, mTORopathies are a group of genetic diseases that confer a high degree of susceptibility to ASD and epilepsy, highlighting the importance of mTOR in epileptogenesis and the development of autism." (PMID 34308255, 2021). "By analyzing the NPRL3-mTOR signaling pathway in family members in vivo, we confirmed the epilepsy was associated with decreased NPRL3 protein expression levels and increased mTOR pathway activity." (PMID 34868250, 2021). "Pathogenic variation in genes encoding regulators of the mTOR cascade cause epilepsies, malformations of cortical development (MCD) and neurodevelopmental disorders." (PMID 34632383, 2021). "KEGG suggested that the Wnt signaling pathway is related to Alzheimer’s disease, while the mTOR signaling pathway, which the protein is also involved in, is causative to diseases such as autism and epilepsy, which are related to ID." (PMID 32858868, 2020). "In previous research regarding mTOR-associated epilepsy, structural abnormalities of neurons have been considered the primary etiologic factor." (PMID 31978189, 2020). "In the present study, we found that mTOR hyperactivation resulting from loss of Tsc2 in Mitf-M-derived cell lineage was associated with the development of typical epilepsy, mitochondria hyperproliferation, and aberrant intracellular calcium dynamics." (PMID 31978189, 2020). "In a previous study, we have shown that DNA methylation regulated potential gene networks, pathophysiological pathways including PDGFR, EGFR, NTRK3(RTKs) as well as mTOR signaling and several other potential epilepsy-related genes associated with FCD type II." (PMID 33192309, 2020). "Neuronal mTOR hyperactivity influences the severity of epilepsy and associated neuropathology in experimental models of TSC." (PMID 32705817, 2020). "Variants in at least 10 genes in the mTOR signaling network, including MTOR, are known to cause epilepsy, autism, and intellectual disability." (PMID 32125271, 2020). "Aberrant mTOR pathway signaling has been extensively characterized in genetically-determined epilepsy in patients with mutations in the Tsc1/2 genes in the context of TSC." (PMID 31978189, 2020). "In epilepsies, many of the mutations in the mTOR pathway that lead to brain malformations are somatic mosaic mutations." (PMID 32201576, 2020). "Dysregulation of the mTOR pathway has been implicated in several neurological and neuropsychiatric diseases including epilepsy, Parkinson’s disease, Alzheimer’s disease, cognitive dysfunction, and several syndromes with autistic features." (PMID 32214004, 2020). "The mTOR pathway has been implicated previously as being highly relevant to the development and treatment of epilepsy." (PMID 32714261, 2020). "Accordingly, disturbances of the mTOR signaling pathway are strongly implicated in cognitive diseases and epilepsy." (PMID 33273479, 2020). "Mutations in the mTOR inhibitor genes, TSC1 and TSC2, have been shown to cause overactivity in the mTOR pathway, thus leading to epilepsy in patients with tuberous sclerosis." (PMID 33192961, 2020).